ATG2A (autophagy related 2A)
Description:
Lipid transfer protein involved in autophagosome assembly. Tethers the edge of the isolation membrane (IM) to the endoplasmic reticulum (ER) and mediates direct lipid transfer from ER to IM for IM expansion. Binds to the ER exit site (ERES), which is the membrane source for autophagosome formation, and extracts phospholipids from the membrane source and transfers them to ATG9 (ATG9A or ATG9B) to the IM for membrane expansion. Lipid transfer activity is enhanced by WIPI1 and WDR45/WIPI4, which promote ATG2A-association with phosphatidylinositol 3-monophosphate (PI3P)-containing membranes. Also regulates lipid droplets morphology and distribution within the cell.
Synonyms: KIAA0404; BLTP4A
Tractability: Antibody: UniProt places it where antibodies can reach, with medium confidence. PROTAC: ubiquitination databases record sites on it; its protein half-life has been measured.
Gene: Protein-coding gene on chromosome 11 (64,894,531 to 64,917,245, reverse strand). Ensembl gene ENSG00000110046.
Subcellular location: Preautophagosomal structure membrane; Lipid droplet; Endoplasmic reticulum membrane
Subcellular location (Human Protein Atlas): Vesicles; Nucleoplasm
Gene Ontology:
Molecular function: lipid transfer activity; protein binding; phosphatidylinositol-3-phosphate binding; protein-membrane adaptor activity
Biological process: autophagosome assembly; positive regulation of autophagosome assembly; positive regulation of autophagy; autophagy of mitochondrion; glycophagy; pexophagy; piecemeal microautophagy of the nucleus; reticulophagy; autophagy; intermembrane lipid transfer
Cellular component: endoplasmic reticulum membrane; organelle membrane contact site; phagophore assembly site membrane; lipid droplet; phagophore; phagophore assembly site
Genetic constraint (gnomAD): Loss-of-function variants: 104 observed, 199.45 expected, observed/expected ratio (o/e) 0.52, 90% interval 0.44 to 0.61. The upper end of that interval is the gene's LOEUF score, 0.61, which puts it in group 2 of 6, group 1 being the genes least tolerant of losing a copy. Missense variants: 2,309 observed, 2,554.8 expected, observed/expected ratio (o/e) 0.9, 90% interval 0.87 to 0.94. Synonymous variants: 1,159 observed, 1,121.2 expected, observed/expected ratio (o/e) 1.03, 90% interval 0.98 to 1.09.
Homologues: Orthologues: chimpanzee ATG2A (99% identical), macaque ATG2A (97% identical), dog ATG2A (88% identical), pig ATG2A (87% identical), rat Atg2a (85% identical), mouse Atg2a (85% identical), guinea pig ATG2A (84% identical), tropical clawed frog atg2a (59% identical), zebrafish atg2a (57% identical), Drosophila melanogaster Atg2 (28% identical), Caenorhabditis elegans atg-2 (22% identical). Paralogues in human: ATG2B (44% identical).
Diseases named in the same sentence as ATG2A in open-access papers:
ATG2A is named in the same sentence as 25 diseases in open-access papers, as found by Europe PMC text mining. Sharing a sentence is not in itself a finding about the gene and the disease. The quoted sentences say what the papers report.
hepatocellular carcinoma (10 papers, 2021 to 2025). A malignant tumor that arises from hepatocytes. "YTHDF1, induced by HIF-1α, promotes hypoxia-induced autophagy and hepatocellular carcinoma malignancy through m6A-modified ATG2A and ATG14 dependency." (PMID 40251202, 2025). "ATG2A has been reported as a target of miRNA-541, and its imbalance in hepatocellular carcinoma plays a crucial role in patients’ response to sorafenib treatment." (PMID 34636718, 2021). "Modulating ATG2A expression can prolong the overall survival of patients with hepatocellular carcinoma by eliminating drug resistance." (PMID 34636718, 2021). "ATG2A is an essential core member of the autophagy machinery, and its upregulation can promote autophagy, potentially contributing to the development of tumors, such as glioblastoma and hepatocellular carcinoma." (PMID 40446009, 2025). "ATG2A can promote the development of hepatocellular carcinoma through miR-541." (PMID 37460467, 2023). "For instance, HIF-1α has been shown to directly stimulate the transcription of YTHDF1, thereby facilitating hepatocellular carcinoma (HCC) autophagy and malignancy by enhancing the translation of ATG2A and ATG14." (PMID 40136363, 2025). "Additionally, the reader YTHDF1 could promote translation of autophagy-related genes ATG2A and ATG14 by binding to m6A-modified ATG2A and ATG14 mRNA, which facilitated autophagy and autophagy-related human hepatocellular carcinoma progression." (PMID 36347025, 2022).
Obesity (2 papers, 2022 to 2024). Accumulation of substantial excess body fat. "Our findings also suggest that lower expression of ATG2A, a gene we found to be associated with BMI, may be both a cause and consequence of obesity." (PMID 39276247, 2024).
breast carcinoma (1 paper, 2024). "ATG2A exhibits mutations in breast cancer, FRMD8 plays a tumor-suppressive role in breast cancer progression, ARSG is negatively correlated with positive prognosis, and differentially expressed genes upregulated by SAC3D1 are involved in regulating the cell cycle pathways in breast cancer cells." (PMID 39720180, 2024).
chronic kidney disease (1 paper, 2017). Impairment of the renal function secondary to chronic kidney damage persisting for three or more months. "Among polymorphisms identified in the present study, rs76974938 [C/T (D67N)] of C21orf59 and rs188780113 [G/A (R478C)] of ATG2A may be novel determinants of estimated glomerular filtration rate and chronic kidney disease or of the serum concentration of uric acid, respectively." (PMID 28410202, 2017).
colitis (1 paper, 2018). Inflammation of the colon. "Similarly, western blotting and immunohistochemical staining showed decreased expression of Erbin, increased expression of LC3B, decreased expressions of ATG16L1 and ATG2A in DSS-induced colitis mice and IL-10-/- mice compared with that in control mice." (PMID 29552291, 2018).
Crohn disease (1 paper, 2024). A gastrointestinal disorder characterized by chronic inflammation involving all layers of the intestinal wall, noncaseating granulomas affecting the intestinal wall and regional lymph nodes, and transmural fibrosis. "We describe the case of a 16-year-old patient with refractory nephrotic syndrome (NS) diagnosed at the age of 6 years, notably with a heterozygous mutation of the ATG2A gene, who developed Crohn's disease (CD) following ten administrations of RTX." (PMID 39633821, 2024). "We report the case of a 16-year-old patient with NS and an ATG2A mutation who developed Crohn's disease (CD) following multiple administrations of RTX." (PMID 39633821, 2024).
Granuloma (1 paper, 2024). A compact, organized collection of mature mononuclear phagocytes, which may be but is not necessarily accompanied by accessory features such as necrosis. "We reviewed his previous gene report and were surprised to find that, beyond the existing LMX1B mutation, the patient carried a heterozygous mutation in the ATG2A gene (chr11:64673862, c.3127G>A, p.1043, P>S), a risk factor for CD with granuloma." (PMID 39633821, 2024). "A cohort study of surgically treated CD patients revealed that the presence of high risk variants of the autophagy gene ATG2A represents a risk factor for CD with granulomas." (PMID 39633821, 2024).
hyperuricemia (1 paper, 2017). An abnormally high level of uric acid. "The remaining four genes (ATG2A, ACOT11, TRIM7, and NOTCH2) may be novel loci that influence the serum concentration of uric acid or confer susceptibility to hyperuricemia." (PMID 28410202, 2017). "We also identified rs188780113 [G/A (R478C)] of ATG2A as a novel determinant of the serum concentration of uric acid as well as rs115445569 of ACOT11, rs116911833 of TRIM7, and rs60854092 of NOTCH2 as potential novel susceptibility loci for hyperuricemia." (PMID 28410202, 2017).
liver fibrosis (1 paper, 2018). "Together, the current study provides insights into the mechanisms underlying autophagy and HSC activation/reversion via ATG2A, and suggests a potential therapeutic benefit for mitigating liver fibrosis by targeting this protein." (PMID 29915313, 2018). "However, more basic biomedical studies and even clinical studies are still needed to confirm the effects of ATG2A depletion on liver fibrosis treatment." (PMID 29915313, 2018). "ATG2A could represent a potential new drug target for hepatic fibrosis." (PMID 29915313, 2018).
nasopharyngeal carcinoma (1 paper, 2025). A carcinoma arising from the nasopharyngeal epithelium. "Neither nasopharyngeal carcinoma (NPC) nor normal nasopharyngeal mucosal tissues exhibited positive expression of the ATG2A protein." (PMID 40630202, 2025).
schizophrenia (1 paper, 2022). A major psychotic disorder characterized by abnormalities in the perception or expression of reality. "The authors also reported an association between the AGA immune response and ATG2A or HLA-DQ2/DQ8 in CD patients, but not in patients with schizophrenia, proposing that AGA immune response in schizophrenia is independent of the action of transglutaminase enzyme and HLA-DQ2/DQ8." (PMID 36555205, 2022).
tuberculosis (1 paper, 2024). A chronic, recurrent infection caused by the bacterium Mycobacterium tuberculosis. "Subsequently, we further verified the transcription levels of genes on anti-tuberculosis-related genes such as CCL1, IL15, IL16, ISG15, GBP5, IL23, ATG2A, IFNβ, and CSF3." (PMID 38392218, 2024). "The expression levels of certain genes related to anti-tuberculosis were further confirmed, such as CCL1, IL15, IL16, ISG15, GBP5, IL23, ATG2A, IFNβ, and CSF3." (PMID 38392218, 2024). "Rv1476 overexpression inhibited the expression of some anti-tuberculosis-related genes, such as CCL1, IL15, IL16, ISG15, GBP5, IL23, ATG2A, IFNβ, and CSF3." (PMID 38392218, 2024).
tumor (7 papers, 2021 to 2025). "In tumor cells, multiple autophagy-related proteins, such as Atg2A and Atg14L, are localized at LDs and participate in the formation of early autophagosomal membranes to facilitate the high lipid turnover, tumor cells tumorigenesis, and metastasis." (PMID 38500157, 2024). "In addition, the present study revealed a mechanism by which lncRNAs can upregulate the expression of ATG2A by combining with hnRNPK, thus promoting autophagy and tumor growth." (PMID 37460467, 2023). "The reader YTHDF1 promotes tumor progress by influencing ATG2A, ATG14, and HIF-1α." (PMID 36059442, 2022). "Similarly, ATG2A or ATG14 downregulation in Hep3B cells counteracted the stimulative effect of YTHDF1 overexpression on tumor growth." (PMID 33619246, 2021). "We established an orthotopic GBM tumor model and demonstrated that knockdown of MGCG inhibited the development of GBM; additionally, the expression of hnRNPK and ATG2A was elevated in the clinical samples of GBM with high expression of MGCG." (PMID 37460467, 2023). "Finally, KO of autophagy-related genes enhanced cell death in the presence of IFN-γ (ATG2A, ATG5, ATF3, and ATF16L1), consistent with autophagy mediating cancer cell resistance to anti-tumor T cells." (PMID 36669486, 2023).
cancer (4 papers, 2017 to 2025). A tumor composed of atypical neoplastic, often pleomorphic cells that invade other tissues. "The ATG2A gene can increase the number and size of cytoplasmic lipid droplets to provide energy for cancer cells." (PMID 30460069, 2017). "ATG2B, ATG2A, ULK1, and RB1CC1 had a wide range of mutation frequencies in the pan-cancer analysis." (PMID 34636718, 2021). "First, in terms of immune function, variations related to the nuclear factor kappa B (NF-κB) signaling pathway (NLRP12, TNIP2, IRAK4) and the autophagy process (TECPR1, ATG2A, SOGA1, TOM1) were identified in both carcinoma and sarcoma tumor groups." (PMID 40446009, 2025).
infection (1 paper, 2024). The state of being infected such as from the introduction of a foreign agent such as serum, vaccine, antigenic substance or organism. "In human iPSC-derived neurons, the increase in cytotoxicity by infection with ATG2A lentivirus was rescued by co-treatment with MitoTEMPO." (PMID 38454050, 2024).
neurodegenerative disease (1 paper, 2023). A disorder of the central nervous system characterized by gradual and progressive loss of neural tissue and neurologic function. "Strikingly, mutations of two of the residues at the same position in WIPI4 and Hsv2, which have been identified in patients with the neurodegenerative disease BPAN, prevent the interaction between Hsv2/WIPI4 and Atg2/ATG2A." (PMID 37989223, 2023).
ATG2A also shares sentences with these, for which no sentence is quoted: gastric cancer (2 papers); glioblastoma (2); cardiovascular diseases (1); glioma (1); hyperlipidemia (1); liver (1); nephrotic syndrome (1); prostate carcinoma (1); vitiligo (1).